IFITM2 (interferon induced transmembrane protein 2)
Diseases named in the same sentence as IFITM2 in open-access papers (continued):
Sharing a sentence is not in itself a finding about the gene and the disease.
infection (continued). "Moreover, it has been demonstrated that increasing the amount of IFITM3 protein in IFITM2/3 knockout cells reduces the infection of cells with the influenza virus, depending on the level of the added IFITM3 protein." (PMID 35216030, 2022). "Therefore, nuclear translocation of TFEB is associated with IFITM2/3 degradation and increased cellular susceptibility to SARS-CoV-2 Spike-mediated infection." (PMID 33880473, 2022). "Therefore, nuclear translocation of TFEB was associated with IFITM2/-3 degradation and increased cellular susceptibility to SARS-CoV-2 spike–mediated infection." (PMID 36264642, 2022). "Interestingly, while IFITM proteins inhibit the entry of all the other human CoVs, HCoV-OC43 hijacks human IFITM2 or IFITM3 as entry factors to facilitate its infection of host cells." (PMID 32641482, 2020). "Interestingly, the JSRV pseudovirion infection in HTX cells was inhibited by IFITM1 (p<0.01) to a much greater extent than by IFITM2 and 3 (p<0.01 and p<0.05, respectively)." (PMID 23358889, 2013). "In addition, a decrease in infection was also observed when the level of IFITM2 was restored." (PMID 35216030, 2022). "Therefore, rapamycin derivatives may facilitate infection by antagonizing constituents of intrinsic immunity, including IFITM2/3, and this activity is determined by the chemical moiety found at carbon-40 of the macrolide structure." (PMID 33880473, 2022). "To continue to explore the potential role of IFITM2 and IFITM3 in CHIKV-IOL infection specifically, we took advantage of the fact that CHIKV-IOL can infect hCFs, which also expresses IFITM3 at the RNA level." (PMID 39314478, 2024). "In the case of HIV-1 restriction, it has been demonstrated that target cells expressing IFITM2 and IFITM3 on their membranes can protect themselves from infection by inhibiting the fusion between the viral envelope and the cellular membrane." (PMID 38400030, 2024). "While IFITMs have widely been demonstrated to inhibit infection, in hCoV, OC43, IFITM2, and IFITM3 have been shown to increase viral entry into cells." (PMID 37985854, 2024). "Surprisingly, we found that IFITM2/3 was increased with DEHP treatment, and genetically silencing IFITM2 and IFITM3 significantly reduced infection." (PMID 39772131, 2024). "TVs expressing sgRNAs targeting known RFs like TRIM5, IFI16, IFITM2, SAMHD1, GBP5 and IFITM1 were enriched after 15 and 20 days post-infection confirming that targeting RFs provides a selection advantage to the respective viruses." (PMID 38714682, 2024). "Moreover, IFITM2 and 3 are suggested to act as cofactors for SARS-CoV-2 in some cases, and we and others also see enhancement of early-lineage isolates and Alpha and Delta infection by IFITM2/3, therefore it cannot be excluded that Omicron may similarly exploit IFITMs in some settings." (PMID 36693093, 2023). "For ST1, inhibition of infection by IFITM1, IFITM2 and the IFITM3 43AS mutant, which shows broader subcellular localization than IFITM3, was significant." (PMID 36851478, 2023). "Our results showed that overexpression of IFITM1, IFITM2, IFITM3, or LY6E significantly inhibited the infection of CCoV-HuPn-2018pp and HCoV-229Epp." (PMID 37676001, 2023). "To test the link between infection enhancement and downmodulation of IFITM proteins by rapalogs, we probed for levels of IFITM3, IFITM2, and IFITM1 by immunoblotting whole cell lysates using specific antibodies." (PMID 33880473, 2022). "Transcripts of effector IFN-induced cell membrane proteins IFITM2 and IFITM3 are increased throughout the infection time course." (PMID 35443155, 2022). "At the same time, HeLa clones with a complete knockout of both IFITM2 and IFITM3 or the three isoforms simultaneously demonstrated the increase in the infection level by more than 20 times." (PMID 35216030, 2022).
infection (continued). "Interferon-induced transmembrane proteins (specifically IFITM-1, IFITM-2, and IFITM-3) have been previously shown to be induced following the infection of viruses, ranging from Influenza A to Ebola to HIV." (PMID 36298693, 2022). "This correlates with resistance to an entry restriction mediated by interferon-induced transmembrane protein 2 (IFITM2) and a pronounced infection enhancement by IFITM3." (PMID 36350154, 2022). "While IAV-LP infection was reduced in HFF, MLV-LP infection was enhanced by overexpression of all IFITMs, significantly for IFITM2 and IFITM3." (PMID 34933450, 2021). "KD of IFITM2 and, to a lesser extent, IFITM3 enhanced the number of S/ACE2 PLA foci after infection of Calu-3 cells with genuine SARS-CoV-2." (PMID 34321474, 2021). "Of note, we observed that several duck IFN-stimulated genes (ISGs), including IFI35, Mx, ISG15, ZC3HAV1, LGP2, IFITM1, IFITM2, and Viperin, were dramatically upregulated upon DTMUV infection." (PMID 34335626, 2021). "After 44 h, the level of HSV infection (MOI of 0.01) in IFITM1-expressing A549 cells was 36.6%, compared to 75.5% and 58.1% for IFITM2 and IFITM3, respectively, and 75.1% infection of control empty vector-transduced cells." (PMID 30567988, 2019). "We therefore studied viral production effects driven by IFITM2 and IFITM3 with dual-tropic HIV-1 89.6, wherein cells were treated with the CXCR4 antagonist AMD3100 prior to and during infection." (PMID 30266929, 2018). "We noticed that infection by the dual tropic HIV-1 89.6 in U87.CD4.CCR5 cells was almost equivalently inhibited by IFITM1 and IFITM2; however, IFITM3 still exhibited the strongest inhibition among all three IFITMs." (PMID 30087232, 2018). "The results showed that the expression of porcine IFITM1 or IFITM1-HA protein, but not IFITM2/3, significantly increased the infection of cells by PEDV-HM." (PMID 40353666, 2025). "Myeloid dendritic cells in dormant infections also showed notable differences in mRNA expression, affecting neutrophil recruitment (C1QA, C1QB, ITGAM), immune checkpoint regulation (IFITM2, IFITM3, CST7, THBS1), and T-cell response (VISIG4, V-set immunoglobulin domain containing 4)." (PMID 39563367, 2024). "Two recent studies suggest that mislocalised IFITM2 and IFITM3 promoted infection with SARS-CoV-2." (PMID 37111405, 2023). "In the case of LACV and ANDV, overexpression of any of the three IFTMs significantly suppressed infection, while only IFITM-2 and IFITM-3 could suppress infection by RVFV." (PMID 36298693, 2022). "Although it was surprising that mislocalization of IFITM2 resulted in enhancement of infection rather than simply an absence of restriction, these data are consistent with a recent report suggesting that similar mutants of IFITM3 enhance SARS-CoV-2 infection." (PMID 33563656, 2021). "Interestingly, infection studies in A549 cell lines shows IFITM3 has greater antiviral activity against IAV and SARS-CoV-2 infection, whereas IFITM2 is more active against EBOV, that enter host cells through interactions with NPC1 in late endosomes." (PMID 34981045, 2021). "In the case of IFITM, the four members (IFITM-1, IFITM-2, IFITM-3, and IFITM-5) are present in endosomes and lysosomes and have a critical role in the inhibition of viruses that require vesicles for effective infection." (PMID 32455136, 2020). "IFITM2 and IFITM3 disrupted the early steps (entry and/or uncoating) of DENV and WNV infection." (PMID 32455136, 2020). "However, the overexpression of IFITM1, IFITM2, and IFITM3 is unable to inhibit the infection of human papillomavirus (HPV), human cytomegalovirus (HCMV), and adenovirus type 5 (Ad5) although type I IFNs can efficiently reduce HPV infection." (PMID 31156602, 2019). "These top genes included IFITM1 and IFITM2, which were significantly expressed between the acute and post-acute visit, but not between infants with severe versus mild infection, and CCR7, which has been found to be downregulated in RSV patients." (PMID 31554845, 2019).
infection (continued). "IFITM2 and IFITM3 impede viral membrane fusion with endosomes to restrict RVFV infection." (PMID 31156602, 2019). "In both cases, statistical analysis indicated that infection by VSV-G pseudotypes was significantly different than HIV-1 wt either in the presence of IFNα or in untreated cells lacking IFITM2 and IFITM3." (PMID 29554922, 2018). "THP1 cells transduced with lentivectors encoding Non-Targeting Control (NTC) or IFITM2/3-targeting sgRNAs were infected with either HIV-1∆env(VSV-G), which is only able to perform one cycle of infection, or with wild-type HIV-1." (PMID 29554922, 2018). "However, viral sensitivity to IFITMs, particularly IFITM2 and IFITM3, increases over the first 6 months of infection, primarily as a result of neutralizing antibody escape mutations." (PMID 27640936, 2016). "We therefore examined gene expression for several important interferon-related genes (IFNα2, IFNα4, IFNβ, IFNαβR, IFNγ, IFNγR, Irf3, Irf7, Mx1, Oas1, IFITM1, IFITM2), along with inflammasome-related genes IL-1β and NLRP3, and chemokines CCL5, CCL7, and CCL12 at d1 post-infection." (PMID 26110868, 2015). "No induction of IFITM2 was detected up to 72 h post infection, indicating that ISG expression was indeed controlled at a post-transcriptional level during DENV-2 infection." (PMID 24992036, 2014). "Robust inhibition of infection was also observed upon IFITM2 expression in A549 and 293T cells but not in MDCK, potentially due to differences in expression efficiency." (PMID 24842154, 2014). "With the insertion of K1L and C7L, this response was tempered; infection with NYVAC-C-KC-ΔB8RΔB19R induced increased transcriptional levels of seven of the genes shown, relative to NYVAC-C-KC (IFI35, IFI44, IFI44L, IFIT1, IFIT3, IFITM1, and IFITM2)." (PMID 22096477, 2011). "However, in response to infection, male mice exhibited higher expression levels of CXCL2 (KO, 1A3, and 6A2), SAMHD1 (1A0, 1A3), RSAD2, STAT1, and STAT3 (1A0), MYD88 and PSMB8 (1A3), BCL3, BCL10, CCRL2, IFITM2, RTP4, and ZFP36L1 (6A2), compared to females." (PMID 32670284, 2020). "By contrast, IFITM2 and IFITM3 did not inhibit but rather enhanced infection in agreement with previous studies." (PMID 36693093, 2023). "We recently utilised a doxycycline (DOX)-inducible protein overexpression system in A549 airway epithelial cells to demonstrate that IFITM1, IFITM2, and IFITM3 are cellular host factors that inhibit IAV but not parainfluenza virus (PIV)-3 infection." (PMID 37111405, 2023). "We suggest that IFITM1, unlike IFITM2 and IFITM3, primarily functions through alteration of the plasma membrane and, as such, is able to restrict viruses at this initial point in infection." (PMID 30567988, 2019). "We show that normal infection by both SFV and SINV is restricted by IFITM3 and, to a lesser extent, by IFITM2, but not by IFITM1." (PMID 27219333, 2016). "The late endosomal IFITM2 is less restrictive and the plasma membrane IFITM1 does not inhibit normal infection by either virus." (PMID 27219333, 2016). "IFITM1 also moderately, but consistently, inhibited the infection by amphotropic 10A1 MLV pseudovirions (p<0.05), yet IFITM2 and 3 did not inhibit and even somewhat enhanced entry." (PMID 23358889, 2013). "Also, no change in the basal mRNA levels of above ISGs (except IFITM2) between control and NAA60-depleted cells was observed without the infection." (PMID 35095845, 2021). "Similarly, infection of these cells with PLVs and replication-competent SARS-CoV-2 at an MOI of 0.005 revealed that infection was not inhibited but rather was enhanced by the presence of IFITM2-Y19F." (PMID 33563656, 2021).
tumor (25 papers, 2012 to 2025). "In recent years, however, a growing number of studies have shown that IFITM2 is associated with tumor development and often plays an important role in oncogene expression." (PMID 38802621, 2024). "The PI3K and p38 MAPK signaling pathways are activated after the BAG3 protein binds to IFITM2 exposed on the surface of tumor-associated macrophages." (PMID 36466909, 2022). "Two genes were found to be independently associated with tumor size (pT4 vs pT1-3): IFITM2 and CD79A." (PMID 33110100, 2020). "Finally, IFITM2, a pro-apoptotic gene, encoding a protein which has been linked to protection against tumour proliferation, was found downregulated in the CDH1-TANGO6 deletion clone." (PMID 37249750, 2023). "In our analysis of 644 cases of CRC, higher IFITM2 expression was positively correlated with tumor N, M, and pathological stages." (PMID 38802621, 2024). "CRC patients with high IFITM2 expression had an increased risk in the late N, M, and pathological stages of the disease, suggesting that IFITM2 is a tumor-related gene." (PMID 38802621, 2024). "The tumor’s pathologic stage, M stage, N stage, and IFITM2 expression levels were used to construct a clinical prognostic risk score for CRC." (PMID 38802621, 2024). "In conclusion, this study confirmed that IFIMT2 is highly expressed in CRC and the high expression of IFITM2 activates PI3K/AKT signaling pathway within tumor cells and promotes the proliferation and metastasis of CRC." (PMID 38802621, 2024). "On the basis of these theories, we have identified a subtype of TAM (CX3CR1_macro) with abundant production of BAG3, which can combine with IFITM2, leading to tumor metastasis." (PMID 35935940, 2022). "Increased levels of the IFITM1, IFITM2, and IFITM3 proteins cause higher proliferation of tumor cells, facilitate migration and invasion and influence crosstalk between tumor and immune cells." (PMID 36466909, 2022). "IFITM1 and IFITM3 are both overexpressed in most tumor tissues, whereas IFITM2 is overexpressed in only some tumor types and even downregulated in others." (PMID 36466909, 2022). "What’s more, CX3CR1_macro significantly secreted BAG3, a multifunctional protein, which can combine with a specific receptor IFITM2 to induce the release of factors that sustain the growth and metastasis of tumor." (PMID 35935940, 2022). "The malignant mutation event was localized to the tumor cell clusters with shared mutation of ANK1 and IFITM2 in all malignant subpopulations of all MM patients." (PMID 36131282, 2022). "Although IFITM2 is less frequently mentioned in tumor-focused studies, this protein seems to act in a similar manner to IFITM1 and IFITM3." (PMID 36466909, 2022). "miR-190 is involved in the regulation of several tumor suppressor genes, including CASP1, IFI6, IFITM2 and OAS1, which are associated with the induction of cell apoptosis and interferon response pathways." (PMID 37304648, 2021). "A recent study found that BAG3 can bind to a specific receptor, such as IFITM2, expressed on macrophages, and induce the release of factors that sustain tumor growth and metastasis." (PMID 30081850, 2018). "Immunofluorescence staining shows that the protein expression of PI gene Ifitm2/3 is markedly elevated in the tumor organoids and is mostly suppressed by sulindac treatment." (PMID 27386949, 2016). "The findings demonstrated that high IFITM2 expression in CRC was markedly related to the tumor N (OR = 1.396 for N0 vs. N1 and N2), M (OR = 1.625 for M0 vs. M1), and pathologic stages (OR = 1.413 for stage I vs. stage II, stage III, and stage IV) (all p < 0.05)." (PMID 38802621, 2024). "Furthermore, the overexpression of Ifitm2 and Ifitm3 within the tumor cell contributes to tumor progression and metastasis." (PMID 38919617, 2024).
tumor (continued). "Furthermore, in general, IFITM3 is expressed at the highest level, and IFITM2 is expressed at the lowest level in normal and tumor tissues (the GTEx Portal)." (PMID 36466909, 2022). "In contrast to IFITM3, IFITM1 and IFITM2 are less frequently assessed in tumor-focused studies." (PMID 36466909, 2022). "By contrast, 4 down-regulated genes are tumor suppressors (Lxn, Rassf4, Dusp16, Ifitm2)." (PMID 25229630, 2014). "However, whether IFITM2 can induce tumour progression by PI3K/AKT signaling pathway in CRC remains to be elucidated." (PMID 38802621, 2024). "Indeed, its interaction with IFITM2 (Interferon Induced Transmembrane Protein 2) on the plasma membrane can induce pro-tumoral cytokine release by macrophages and fibroblasts, thus sustaining tumor growth." (PMID 37835519, 2023). "IFITM2 was over-expressed in the CRC tissues and cells, with high IFITM2 expression related to the tumor N, M, and pathologic stages." (PMID 38802621, 2024). "IFITM1, IFITM2 and IFITM3 have miscellaneous functions including cell adhesion, antiproliferation, tumor suppression and embryonic development." (PMID 23166625, 2012). "IFITM1, IFITM2 and IFITM3 are involved in cell adhesion, antiproliferation, tumor suppression, and germ cell and embryonic development." (PMID 23166625, 2012). "This review summarizes and discusses current knowledge of IFITM proteins, especially the immune-related proteins IFITM1, IFITM2 and IFITM3, different levels of regulation of their expression and function, and their involvement in immune processes and tumor transformation." (PMID 36466909, 2022). "Therefore, IFITM2 is expected to be an effective target to improve the prognosis of CRC patients, and this study also provides some experimental basis for the targeted intervention of PI3K/AKT pathway-related molecules in the treatment of tumor metastasis." (PMID 38802621, 2024). "Here, we provide a summary of the current knowledge on the roles of the IFITM1, IFITM2 and IFITM3 proteins in different types of tumors and the molecular mechanism, effect on anticancer therapy and links between IFITM-interacting partners with an overlap with tumor progression." (PMID 36466909, 2022).